REV1 (REV1 DNA directed polymerase)
Diseases named in the same sentence as REV1 in open-access papers (continued):
Sharing a sentence is not in itself a finding about the gene and the disease.
cancer (30 papers, 2018 to 2025). A tumor composed of atypical neoplastic, often pleomorphic cells that invade other tissues. "Studying REV1 will increase our understanding of the origin of cancer, as mutations are an important feature of cancer development." (PMID 36246647, 2022). "Unexpectedly, we discovered that REV1 inhibition by small molecule inhibitors triggered autophagy, which is known to cause therapy resistance in cancer cells under certain conditions." (PMID 34771454, 2021). "In contrast, a similar reduction in functional REV1 during radiation treatment or drugs that cause strand breaks in cancer cells will propel therapy resistance because REV1 inhibition evokes a newer function of induction of autophagy." (PMID 34771454, 2021). "We summarize the available data from ours and others’ in vivo studies on the role of Rev1 in the initiation and promotion of cancer, emphasizing how Rev1-mutated mouse models can be used as complementary tools for future research." (PMID 32161626, 2020). "We found a relatively weak contribution of REV1 and UNG mutation or silencing to APOBEC mutagenesis in human cancers, which nevertheless confirms the expected trend: on average, samples defective for REV1 or UNG display an 8% decrease in C > G mutations." (PMID 32358516, 2020). "A number of studies indicate that REV1 has been linked to the development of some cancers." (PMID 36246647, 2022). "More recently, Rev1 has also been implicated in replication-induced gap filling, which may be a vulnerability in cancer cells." (PMID 35610266, 2022). "Mutations in human REV1 have been detected in a minority of tumors, and single-nucleotide polymorphisms (SNPs) in the hREV1 gene have been linked to various types of human cancer." (PMID 32161626, 2020). "However, indications that REV1 inhibition can also switch the underlying biology of cancer cells, whereby it can suppress apoptosis in cisplatin-treated cells and trigger senescence, suggested that REV1 may have a larger new role in cancer pathogenesis." (PMID 34771454, 2021). "Because REV1 functionally links DSBR with enhanced mutations and REV1 inhibitors suppress apoptosis and trigger senescence to sensitize cancer cells to chemotherapy, it is unknown whether REV1 may similarly sensitize cancer cells to radiation therapy and prevent radioresistance." (PMID 34771454, 2021). "These different evolutionary stages, along with the cell-type and time-specificities of cancer cells, are important avenues for future research to fully understand how REV1 limitation over time fundamentally influences cancer versus normal cell-cycle dynamics." (PMID 41595464, 2025). "Taken together, our data suggested that REV1 protects cancer cells against the cytotoxic effects of oncogene activation." (PMID 36759509, 2023). "Pan-cancer single nucleotide variation analysis showed that the overall average mutation frequency ranged from 0 to 8.2%, and CRGs including AUTS2, TIMELESS, REV1, and PER2 showed high mutation frequencies." (PMID 36895015, 2023). "Abolishing this gap filling role with an inhibitor that disrupts the interaction between REV1 and MAD2L2/REV3L is toxic to these HR-deficient cancer cells, including to PARP inhibitor-resistant BRCA1 mutant cells." (PMID 36075897, 2022). "In contrast, low REV1 expression was observed in only eight cancer types, namely, BLCA, BRCA, KICH, KIRC, KIRP, PRAD, THCA, and UCEC." (PMID 36246647, 2022). "We found that REV1 was overexpressed in six cancer types, namely, CHOL, ESCA, HNSC, LIHC, LUSC, and STAD." (PMID 36246647, 2022). "In our studies, we also focused on the role of REV1 in various cancers as a prognostic biomarker and the potential function of REV1 regulating the sensitivity of tumor cells to specific drugs." (PMID 36246647, 2022).
cancer (continued). "REV1 inactivation using the small molecule inhibitor JH-RE-06 (referred from here on REV1i) has been proposed to chemosensitize cancer cells to cisplatin." (PMID 35819193, 2022). "REV1 as a potential prognostic biomarker, our research found REV1 gene alterations are related to PFS prognosis in pan-cancer samples while nsSNP F427L is predicted to be deleterious SNP." (PMID 36246647, 2022). "This study aimed to explore the role of REV1 as a prognostic biomarker and its potential function regulating the sensitivity of anti-tumor drugs in various cancers." (PMID 36246647, 2022). "The IC50 values of anti-cancer drugs were downloaded from the Genomics of Drug Sensitivity in Cancer database and the correlation analyses between REV1 expression and each drug pathway’s IC50 value in different tumor types were conducted." (PMID 36246647, 2022). "We also explored the link between the expression of REV1 and cancer patient outcome as well as the correlation between REV1 expression and IC50 of various drugs in different tumor types." (PMID 36246647, 2022). "In this context, REV1 inhibition has been reported to be toxic to cancer cells in unperturbed conditions." (PMID 35819193, 2022). "The Kaplan-Meier plotter database was also employed to assess the relationship between REV1 expression and patient prognosis in a range of cancer types." (PMID 36246647, 2022). "This study shows two unexpected observations that further our understanding of REV1 functional dynamics during cancer resistance and the consequences of targeting REV1 during different DNA-damaging cancer treatments." (PMID 34771454, 2021). "Targeting the mutagenic translesion synthesis (TLS) polymerase REV1 was previously shown to sensitize cancer cells to chemotherapy." (PMID 34771454, 2021). "In the last few years, the translesion synthesis pathway, especially the REV1 polymerase, has gained considerable traction in understanding how cancers acquire intrinsic and acquired resistance to therapy." (PMID 34771454, 2021). "Previously, REV1 inhibitors that targeted specific interfaces of this CTD were shown to sensitize cancer cells to chemotherapy treatment, which suggested that the REV1-dependent DNA damage bypass of chemotherapy-induced damage was the cause of chemoresistance." (PMID 34771454, 2021). "Small molecule inhibitors of the TLS PPIs are promising candidates for cancer therapeutics and also have potential as chemical probes to decipher the various roles of each polymerase in REV1/POLζ-dependent TLS." (PMID 34577015, 2021). "Disruption of REV1/POLζ-dependent TLS in a variety of cancer models restores sensitivity to several genotoxic agents, reduces tumor progression, and can increase overall survival." (PMID 34577015, 2021). "In yeast and cancer cells, Rev1 functions as an indispensable scaffolding component of Polζ and it imposes highly error-prone TLS upon Polζ." (PMID 33514655, 2021). "This study collectively shows that REV1 inhibition confers a cytoprotective effect on cancer therapies aimed at inducing DNA strand breakage." (PMID 34771454, 2021). "We report a possible role of the REV1 TLS protein in determining cancer treatment outcomes depending upon the type of DNA damage inflicted." (PMID 34771454, 2021). "Pol ζ/REV1 plays an essential role in the TLS that usually leads to resistance of cancer cells to chemotherapy." (PMID 32332881, 2020). "Testing candidate NESs in cancer-related proteins allowed us to compare the SRVB/A reporter with the widely used Rev(1.4)-GFP reporter." (PMID 32882917, 2020). "Our analysis of cancer cell line data identified associations of drug sensitivity with expression levels of APOBEC3A, APOBEC3B, REV1, and UNG genes and with abundance of sequence motifs and kataegis clusters attributed to APOBEC activity." (PMID 29642934, 2018).
cancer (continued). "Our study conducted a comprehensive assessment of REV1, explored the role of REV1 in various cancers as a prognostic biomarker and further highlight a potential function whereby REV1 may regulate the sensitivity of tumor cells to specific drugs." (PMID 36246647, 2022). "Inhibiting Rev1 using JH-RE-06 or Rev3 presented promising results for cancer treatment." (PMID 35163901, 2022). "Moreover, both inhibition of PCNA- or REV1-dependent DNA damage tolerance (DDT) have been proposed to chemosensitize cancers to cisplatin, enhancing the efficacy of cancer treatment with platinating agents." (PMID 35819193, 2022). "Finally, our data directly link uracil excision by UNG and REV1-dependent TLS to the acquisition of APOBEC3-induced signatures in human cancer cells." (PMID 35859169, 2022). "Besides a direct role of REV1 in tolerance of genotoxic lesions, recent reports also suggested that it is required for cancer cells to prevent replication stress." (PMID 35819193, 2022). "The expression of the REV1 gene was also found to increasein cancer patients." (PMID 35740268, 2022). "Moreover, REV1 is dispensable for the tolerance of cisplatin lesions in various murine and human cancer cells in vitro." (PMID 35819193, 2022). "This study tested whether REV1 inhibition via CTD-specific small molecule inhibitors sensitizes cancer cells to radiation treatment." (PMID 34771454, 2021). "Because cancer cell lines over the course of cancer treatment tend to acquire resistance to therapy, we tested whether REV1 inhibition may sensitize acquired radioresistant cell lines to radiation treatment." (PMID 34771454, 2021). "Further, we found a narrow range within which an autophagy inhibitor might aid in sensitizing IR and REV1 inhibitor-exposed cancer cells." (PMID 34771454, 2021). "Whether REV1 inhibition would similarly sensitize cancer cells to radiation treatment is currently unknown." (PMID 34771454, 2021). "Similarly, we tested the ability of REV1 inhibitors to sensitize the cancer cells to increasing doses of IR in the cytotoxicity assays and observed no synergy in cytotoxicity." (PMID 34771454, 2021). "It is equally intriguing to evaluate whether REV1 might serve as a clinical biomarker for cancer cell response to other cancer treatments." (PMID 34771454, 2021). "Another potential clue to understanding the evolution of Rev1 may be held in analysis of how G4 structures populate the genomic landscape of cancer cells." (PMID 33555350, 2021). "Furthermore, we discover that REV1 inhibition directly triggers autophagy, an uncharacterized REV1 phenotype, with a significant bearing on cancer treatment regimens." (PMID 34771454, 2021). "Considering that inhibition of Pol ζ, Pol δ or REV3 is toxic to normal cells, and perhaps unlikely to provide a suitable therapeutic index in vivo, inhibitors specifically targeting REV1 or its interaction with POLD3 might be a promising avenue to pursue for the development of a new cancer therapy." (PMID 36759509, 2023). "Interestingly, recently, it was shown that a small-molecule inhibitor targeting the C-terminal domain of REV1 could synergize with DNA-replication-gap inducing cancer treatments." (PMID 36759509, 2023). "Moreover, we reveal that, upon oncogene activation, cancer cell survival is significantly compromised when REV1 is depleted, suggesting that REV1 inhibition might be a feasible approach for the treatment of some human cancers." (PMID 36759509, 2023). "In addition, similarly to PARP1 or DNA polymerase Polθ inhibitors that are used to treat HR-deficient cancers, the small molecule JE-RH-06 disrupts the interaction between the TLS polymerases REV1 and Polζ and shows preferential cytotoxicity in BRCA1-deficient cancer cells." (PMID 36749784, 2023). "Loss of PCNA-ubiquitination, but not REV1 sensitized mammalian cancer cell lines to cisplatin." (PMID 35819193, 2022). "Whether REV1 inhibition would similarly sensitize cancer cells to radiation treatment is unknown." (PMID 34771454, 2021).
cancer (continued). "Alternatively, the underlying signature change may not be detectable due to REV1/UNG mutation occurring late in cancer development compared to APOBEC overactivation." (PMID 32358516, 2020). "In summary, the currently existing data is limited to genome instability and mutagenesis, but carcinogenesis studies on Rev1 KO mice have not been published, and the impact of Rev1 deficiency on cancer development in vivo remains unknown." (PMID 32161626, 2020). "In yeast or cancer cells, Rev1 functions as a scaffolding component of Polζ and TLS by Rev1-Polζ operates in a highly error-prone manner." (PMID 34119520, 2021). "Examination of gene expression measures in the pan-cancer dataset showed a bimodal distribution of APOBEC3B expression, whereas APOBEC3A, REV1, UNG, and FHIT had unimodal distributions of their expression measures." (PMID 29642934, 2018). "We observed a bimodal distribution of APOBEC3B expression and unimodal distributions of APOBEC3A, REV1, UNG, and FHIT in the pan-cancer dataset." (PMID 29642934, 2018). "Recent studies showed that genetic inhibition of TLS through RNA-mediated depletion of Rev1, Rev3 or MAD2L2 indeed sensitizes a variety of cancer cells to DNA-damaging chemotherapeutics and suppresses the emergence of new tumor chemoresistance both in cancer cell lines and animal models." (PMID 35163901, 2022). "Our studies in mice and in mammalian cells strongly indicate PCNA-ubiquitination is the predominant mode of DDT, and that a genetic ablation of REV1 does not sensitize murine and human cancer cells to various classes of clinically approved DNA damaging agents." (PMID 35819193, 2022). "We did not observe synergy between REV1i and cisplatin in any cancer cell line tested, indicating that REV1 inhibition does not chemosensitize mammalian cells to ICLs." (PMID 35819193, 2022). "Notably, REV1- Polζ was recently identified to have a protective and mutagenic role in BRCA1/2 mutant cancer cells by filling in PRIMPOL-dependent ssDNA gaps that arise in these cells upon replication fork stalling at SMUG1-mediated DNA lesions." (PMID 36075897, 2022). "We observed that REV1 inhibition does not sensitize cancer cells to ionizing radiations, where a combination treatment of different REV1 inhibitors and radiation treatment failed to sensitize HT1080, HCT116, and MEF cells." (PMID 34771454, 2021). "In summary, our data suggest that REV1 inhibition does not sensitize cancer cells with intrinsic and acquired resistance to radiation treatment." (PMID 34771454, 2021). "In contrast to their chemosensitization effects, REV1 inhibition failed to sensitize cancer cells to ionizing radiation." (PMID 34771454, 2021). "This study reports a lack of radiosensitization in response to REV1 inhibition by small molecule inhibitors in ionizing radiation-exposed cancer cells." (PMID 34771454, 2021). "Using colony survival assays, our results showed no increased sensitization of these IR-exposed cancer cells to REV1 inhibitors." (PMID 34771454, 2021). "In addition, we could confirm that REV1 and REV3 are essential for MiDAS in other cancer cell lines; namely, HeLa, HCT116, and the HCT116-POLD1-AID2 cell line that we have established in this study." (PMID 36759509, 2023). "In striking contrast, TLS analyses with a variety of DNA lesions present on the template for leading or lagging strand replication of a duplex plasmid carried in normal human cells (not derived from cancers) have shown that Rev1 functions together with Y-family Pols η, ι, or κ and not with ζ." (PMID 33514655, 2021). "First, we found that REV1 inhibition during radiation therapy may not sensitize cancer cells to increased cell death, as indicated by our in vitro data." (PMID 34771454, 2021). "Because reduction of REV1 triggered autophagy and failed to radiosensitize cells, we hypothesize REV1 expression dynamics might link cancer cell response to radiation treatment through the potential induction of autophagy." (PMID 34771454, 2021).
cancer (continued). "Because REV1 plays a role in the DSBR pathway and suppresses apoptosis—processes known to be involved in radioresistance—we hypothesized that REV1 inhibition might sensitize cancer cells to radiation treatment." (PMID 34771454, 2021). "In conclusion, this study suggests that inhibition of the TLS polymerase, REV1, may not be an excellent synergistic approach to treating cancer cells with radiation due to a possible induction of autophagy." (PMID 34771454, 2021). "Whereas many studies have focused on the molecular roles of APOBEC3B, and to some extent APOBEC3A, possible cumulative effects of action of APOBEC3A, APOBEC3B, UNG, REV1, and FHIT on generation of APOBEC3B-like mutation motifs and on drug sensitivity in cancer have not been clearly elucidated." (PMID 29642934, 2018). "To address this question, we investigated the presence of APOBEC3B-like mutational patterns and mRNA expression of the APOBEC3A, APOBEC3B, UNG, REV1, and FHIT genes in cancer cell lines, in order to identify those cancer cell lines that may have experienced kataegis events." (PMID 29642934, 2018). "However, because a functional reduction of REV1 was key in triggering the autophagy and the inhibition of REV1 failed to radiosensitize cells, REV1 expression dynamics may link cancer cell response to radiation treatment through the potential induction of autophagy." (PMID 34771454, 2021). "To further verify if the lack of cytotoxicity from REV1 inhibition during radiation treatment was simply an IR-specific effect, we exposed HT1080 cells to etoposide (a cancer drug that functions like IR by inducing DNA strand-breakages and inducing cytotoxicity) and drugs 4 (7922759) and JH-RE-06." (PMID 34771454, 2021). "Additionally, acquired radioresistant cancer cells REM and ZR751, developed by exposing the parental cells to repeat rounds of IR, survived similarly to non-treated controls when exposed to REV1 inhibitors." (PMID 34771454, 2021). "Considering that oncogene activation is also able to induce RS in cancer cells, and the fact that some of the TLS polymerases are non-essential e.g. REV173, we investigated whether depletion of REV1 might specifically compromise the viability of cells in which oncogenes are activated." (PMID 36759509, 2023).